CRP (C-reactive protein)
Diseases named in the same sentence as CRP in open-access papers (continued):
Sharing a sentence is not in itself a finding about the gene and the disease.
sleep disorder (continued). "CRP may partially mediate the association between dietary vitamin C and sleep disorders." (PMID 39519494, 2024). "We presume that the reason for failure to detect an association between sleep disorders and CRP in some population studies might rest in an incomplete estimation of the sleep disorders, which could be a result of just focusing on one type of sleep disorder/problem but neglecting others." (PMID 24663098, 2014). "Since the close correlation among these sleep disorders may lead to failure in detecting the association of sole sleep disorder and CRP, as we found in this study, a combined index should be more representative than separate components in sleep quality evaluation." (PMID 24663098, 2014). "Inflammatory markers (notably CRP and NLR) mediated 5.3 %-17.9 % of the association between OA and sleep disorders." (PMID 41743392, 2026). "Significant associations between sleep disorders and CKD were observed in participants aged <60, with a BMI <28 kg/m2, normal blood pressure, and CRP ≥1.8 mg/L." (PMID 41340851, 2025). "For instance, evaluated levels of systemic inflammatory markers such as interleukin-6 (IL-6), C-reactive protein, and tumor necrosis factor were observed in individuals with sleep disorder." (PMID 40270512, 2025). "Age, anesthesia time, surgery time, intraoperative blood loss, postoperative hypoxemia, postoperative VAS score, and postoperative CRP level are the influencing factors of postoperative sleep disorders in elderly HR patients undergoing general anesthesia." (PMID 41394003, 2025). "Significant associations were found between sleep disorders and CKD in participants aged <60 years, BMI <28 kg/m2, normal blood pressure, CRP ≥1.8 mg/L, and PIR <2.88." (PMID 41340851, 2025). "Patients with sleep disorders due to acute cerebral infarction displayed increased inflammatory factors, including C-reactive protein (CRP), IL-6, IL-1β, TNF-α and Hcrt, compared with normal levels." (PMID 38671959, 2024). "In line with this, a meta-analysis of 72 studies found a significant relationship between increased levels of IL-6 and CRP with sleep disorders." (PMID 38541200, 2024). "In fact, a prior meta-analysis has demonstrated that sleep disorders and insufficient sleep have elevated levels of c-reactive protein (CRP) and interleukin-6 (IL-6)." (PMID 38408934, 2024). "Studies have found that sleep disorders increase the levels of systemic inflammatory markers such as leukocytes, cytokines, interleukins, C-reactive protein, etc.." (PMID 37202744, 2023). "On the other hand, several studies show how sleep disorders can lead to higher levels of different inflammatory and autoimmune markers in humans, such as higher levels of C-Reactive Protein, Interleucin-6 or Tumor Necrosis Factor." (PMID 36834203, 2023). "The previous study found that, compared with non-drinkers, people who drank ≥4 cups of total coffee/day had lower concentrations of C-reactive protein and interleukin 6 (IL-6), which are related to sleep disorders." (PMID 35215524, 2022). "In terms of sleep quality, a meta-analysis of sleep and frailty showed that sleep disorders lead to high levels of inflammatory markers such as C-reactive protein (CRP) and factor VIII, and these immunological changes are one of the main causes of frailty." (PMID 36091504, 2022). "Further studies have established a bidirectional link between inflammatory biomarkers, such as C-reactive protein (CRP) and interleukin-6 (IL-6 and), and sleep disorders." (PMID 35768855, 2022). "Sleep quality and quantity was assessed by the Sleep Disorders Questionnaire, and fasting blood was collected to quantify CRP, GGT, antioxidant micronutrients, insulin concentration, and HbA1c." (PMID 35757614, 2022). "Personality/behavioral change, speech change, affective disorder, movement disorder, and sleep disorders were seen more often in AE, while fever, elevated CRP, elevated CSF protein, and MRI abnormalities were seen more often in IE." (PMID 36237630, 2022).
sleep disorder (continued). "The results showed that the risk factors for sleep disorders in patients were age ≥60 years, hypercalcium and hyperphosphatemia, substandard PTH, and high CRP." (PMID 34867112, 2021). "This study showed that serum levels of HCY, lipids, and CRP were higher in the sleep disorder group than in the normal group." (PMID 34941184, 2021). "This study focused on 9,317 participants in the National Health and Nutrition Examination Survey (NHANES) from 2005–2008 who were aged 20–85 years, completed a sleep disorder questionnaire, and had available information on serum hs_CRP." (PMID 24663098, 2014). "Additionally, as evidenced by a meta-analysis, patients with sleep disorders were examined with obviously escalated levels of inflammatory markers C-reactive protein (CRP) and IL-6." (PMID 41601533, 2026). "In summary, age, anesthesia time, surgery time, intraoperative bleeding volume, postoperative hypoxemia, postoperative VAS score, and postoperative CRP levels are influencing factors for postoperative sleep disorders in elderly patients undergoing general anesthesia HR surgery." (PMID 41394003, 2025). "Through the utilization of a fully adjusted regression model, our research revealed a significant positive relationship between sleep disorder and hs-CRP (β: 0.94, 95%CI: 0.00–1.87), SII (β: 54.29, 95%CI: 21.04–87.53), SIRI (β: 0.12, 95%CI: 0.02–0.22), and GGT (β: 4.95, 95%CI: 1.21–8.70) levels." (PMID 40270512, 2025). "This study, based on the NHANES database, is the first to delve into the mediating roles of inflammatory response (hs-CRP, WBC, SII, and SIRI) and oxidative stress (GGT, albumin, ferritin, and total bilirubin) in the association between sleep disorder and infertility risk." (PMID 40270512, 2025). "The mechanism may involve preoperative pain control, which can help reduce perioperative IL-6 levels and hs-CRP levels, alleviate postoperative pain and improve sleep disorders." (PMID 40454146, 2025). "C-reactive protein significantly mediated the effect of dietary vitamin C on sleep disorders." (PMID 39519494, 2024). "Disruption of circadian rhythm due to sleep disorders in PWH may lead to immune system dysregulation, resulting in elevated levels of inflammatory molecules, such as interleukin 6 and C-reactive protein, that have been associated with the risk of frailty." (PMID 38033984, 2023). "This could also be because women tend to have higher C-reactive protein (CRP) and interleukin-6 levels, which act as markers in the etiology of frailty A large number of older adults who had sleeping disorders were also found to be frail." (PMID 37438687, 2023). "A systematic review examining inflammation and sleep disorders noted that two inflammatory factors, C-reactive protein (CRP), and IL-6, are strongly associated with sleep disorders, which upregulate the expression of NF-κB and increase the levels of intercellular adhesion molecules." (PMID 38074156, 2023). "For sleep medicine, the following novelty emerges, which should nevertheless be confirmed in its significance in larger collectives: Compared to CRP, ferritin is a more important laboratory marker for screening populations for the possible presence of a sleep disorder." (PMID 36980461, 2023). "When dividing HD patients into good and bad sleepers based on PSQI results, we confirmed our hypothesis regarding higher CRP levels in a sample of HD patients with sleep disorders, which was in accordance with the results of some previous studies." (PMID 35683604, 2022). "Although empirical and clinical studies further confirmed a causal relationship between sleep disorders and higher CRP concentrations, results from population studies on sleep and CRP are not consistent." (PMID 24663098, 2014). "Moreover, about half of our patients, classified in group A, expressed sleep disorders of some extent, mainly for the next two days following CRP, probably because of the awkward sleeping position that they were advised to adopt." (PMID 22518162, 2012).
sleep disorder (continued). "Endorsing simple routine blood tests, including inflammatory markers such as C-reactive protein, ferritin, transferrin, and vitamin D levels, may favorably complement caregiver observations and ambulatory sleep recordings, leading to a sleep disorder diagnosis and consequent therapy." (PMID 36226108, 2022). "However, the exact progressive cause remains unknown with regard to the correlation between HCY, CRP levels, and sleep disorders during the MT period." (PMID 34941184, 2021). "In addition, previous studies have established that sleep disorders can lead to the dysregulation of inflammatory and antiviral responses characterized by increased C-reactive protein, ultimately leading to compromised immune defences, which may explain their effects on multimorbidity." (PMID 41146012, 2025). "Sleep disorders, including RBD and ESS, exhibit significantly altered levels of IL-6, CRP, IL-1β, sTREM2, CCL3 and NO, suggesting these markers represent potential markers in PD patients." (PMID 36739284, 2023). "Sleep disorders promote a low-grade inflammatory status by increasing circulating proinflammatory cytokines (IL-1β, IL-6, IL-17A, TNF-α) and CRP." (PMID 30402295, 2018). "4.Habitual coffee and tea consumption does not influence CRP, serum uric acid, electrolyte and lipid concentrations in sleep disorder patients." (PMID 37229165, 2023). "Results of the correlation analysis showed negative correlations between 25(OH)D and glycolipid metabolic parameters (HbA1c, FPG, PBG), depressive symptomatology (assessed by CES-D sum score), sleep disorders (assessed by PSQI sum sores), and three inflammatory markers (CRP, IL-6, sTREM1)." (PMID 36619542, 2022). "Elevated CRP occurred at a significantly higher rate in respondents with sleep apnea, other sleep disorder, and reported sleep disturbance, compared to no sleep problems." (PMID 30402295, 2018). "While sleep disorders have been suggested to have a bidirectional relationship with inflammation, no study has explored the relationships between abnormal CRP levels and sleep disorders in SZ to date." (PMID 30190688, 2018). "In addition to this, The low levels of vitamin D that are present in HD patients with sleep disorders cannot inhibit the production of proinflammatory cytokines and CRP." (PMID 35683604, 2022). "However, results from epidemiologic studies regarding sleep disorders and CRP are not consistent." (PMID 24663098, 2014). "The present study aims to evaluate two inflammatory markers, C-reactive protein (CRP) and red cell distribution width (RDW), in those with unreported sleep disturbances and compares these findings to those with and without reported sleep disorders." (PMID 30402295, 2018). "The present study was undertaken to compare and contrast CRP and RDW responses in individuals with unreported sleep disturbances to those diagnosed with sleep disorders and those reporting no sleep problems." (PMID 30402295, 2018). "None of the factors significantly influenced sleep disturbances (age, gender, years of education, occupation, marital status, ESR, CRP, disease duration, morning stiffness, fingertip-to-floor distance, BASMI, BASDAI, or BASFI)." (PMID 23058191, 2012).
uveitis (82 papers, 2011 to 2026). An inflammatory process affecting a part of or the entire uvea. "JAKi therapy was associated with a significantly lower risk of uveitis in patients with elevated CRP (≥3 mg/L; HR, 0.50; 95% CI, 0.26–0.96) and elevated ESR (≥20 mm/h; HR, 0.41; 95% CI, 0.19–0.87)." (PMID 41208989, 2025). "Conversely, we noted a lower magnitude of HR associated with cataract risk among pediatric patients with uveitis who had lower levels of CRP and leukocyte count." (PMID 38949811, 2024). "In one study, uveitis was associated with coronary artery dilatation, higher neutrophil count, and higher CRP levels in children with KD." (PMID 38693550, 2024). "Our analysis revealed an elevated risk of cataract development among patients with uveitis, particularly among those possessing CRP levels less than 1 mg/dL and 1 mg/dL or more." (PMID 38949811, 2024). "Elevated C-reactive protein (p = 0.012) was associated with shorter delay in diagnosis, while uveitis (p < 0.001) and younger age at onset of the first symptom (p = 0.002) were associated with longer delay in diagnosis in multiple regression analysis." (PMID 34188149, 2021). "Elevated levels of ESR and CRP reflected systemic involvement and high levels of both values were associated with established uveitis cause." (PMID 30411142, 2019). "In patients with highly elevated ESR and/or CRP, the presence of a systemic disease is very likely, and in consequence, the cause of uveitis is being established in a vast majority of cases." (PMID 30411142, 2019). "Two patients had HLA B27-associated uveitis with systemic involvement of which one had high elevation of CRP ≥ 60 mg/L and ESR ≥ 20 mm/h and the other exhibited normal values." (PMID 30411142, 2019). "Furthermore, findings from our subgroup analysis based on these inflammatory markers showed higher HRs associated with cataract risks among patients with uveitis with CRP levels 1 mg/dL or more compared with those with CRP levels less than 1 mg/dL." (PMID 38949811, 2024). "In addition, according to their research, uveitis is associated with coronary artery dilatation, higher neutrophil count, and higher CRP levels." (PMID 38693550, 2024). "Similarly, patients younger than 18 years with uveitis and CRP levels 1 mg/dL or more also had an increased risk of cataract development (HR, 13.80; 95% CI, 4.26-44.65) compared with those without uveitis." (PMID 38949811, 2024). "In multiple regression analysis, elevated CRP was significantly associated with shorter diagnostic delay, while uveitis and younger age at onset of first musculoskeletal symptom were significantly associated with longer diagnostic delay after adjustment for other variables." (PMID 34188149, 2021). "Younger age at onset, uveitis, and normal CRP were associated with longer diagnostic delay." (PMID 34188149, 2021). "Biomarkers like ESR and CRP are commonly assessed during the diagnostic workup of new uveitis patients for potential detection of infections or systemic immune-mediated disease-causing uveitis." (PMID 30411142, 2019). "Out of 20 patients with either ESR ≥ 60 mm/h and/or CRP ≥ 60 mg/L, the cause of uveitis could be determined in 19/20." (PMID 30411142, 2019). "However, it remains debatable whether ESR and CRP have any diagnostic value in evaluation of uveitis in adult patients having a first uveitis attack of unexplained origin." (PMID 30411142, 2019). "In addition, the changes of ESR and/or CRP might change in individual patients and might be associated with impeding uveitis activity." (PMID 30411142, 2019). "HLA-B27 positive patients were more frequently male (p = 0.004) and had higher rates of uveitis (p = 0.006), family history of SpA (p < 0.001), and elevated CRP levels (p < 0.001)." (PMID 41851765, 2026). "Subgroup analyses showed that the protective effect of JAKi therapy against uveitis was more pronounced in older adults, White individuals, and patients with elevated inflammatory markers (CRP ≥3 mg/L or ESR ≥20 mm/h)." (PMID 41208989, 2025).
uveitis (continued). "We analyzed data on adalimumab dosing intervals, ESR, CRP, and uveitis recurrence at each visit for patients with AS." (PMID 41007651, 2025). "Other studies have reported an elevation of the leukocyte count and CRP levels among patients with uveitis." (PMID 38792893, 2024). "Among the patients with uveitis, the mean (SD) of CRP levels was 2.32 (4.35) mg/dL, and 2.03 (3.82) mg/dL among those without uveitis (to convert to milligrams per liter, multiply by 10.0)." (PMID 38949811, 2024). "Uveitis in KD is significantly associated with coronary artery dilatation, IVIG resistance, higher WBC count, platelet count, and CRP level." (PMID 38693550, 2024). "Our study found that CRP levels were found to be significantly higher in patients with papulopustular lesions, joint involvement, and uveitis symptoms." (PMID 39050391, 2024). "Even though data on uveitis as well as on ocular cicatricial pemphigoid are limited, there is evidence for systemic inflammation and possible CRP increase." (PMID 37873776, 2023). "Based on Wallace criteria 1 (excluding uveitis and CRP), two cases that first reached CID on the last visit (5th year), were excluded." (PMID 36096831, 2022). "Using Wallace criteria 2 (excluding uveitis, CRP and PGA), three cases that attained CID on the last visit were excluded, leaving 93 patients for analysis." (PMID 36096831, 2022). "Data elements that were initially considered, but did not achieve consensus, included fatigue, morning stiffness, mental health, uveitis status, and several laboratory values (C-reactive protein, erythrocyte sedimentation rate, and aspartate aminotransferase)." (PMID 35133283, 2022). "cJADAS-27, ESR and C-reactive protein, as well as uveitis activity, medication at the time of flare and treatment of flare was extracted." (PMID 34844609, 2021). "Of the 32 patients assessed for CRP at the date of uveitis diagnosis, 50% (n = 16) had high levels of CRP." (PMID 34425847, 2021). "Sarcoidosis-associated uveitis showed a predominantly elevated ESR (13/24, 54%; in the range between 20 and 59 mm/h 11/13, 85%), while CRP was most often normal (17/24, 71%)." (PMID 30411142, 2019). "After receiving adalimumab, the active uveitis and visual acuity of patient #5 improved; however, relapsing oral ulcers, and high CRP levels and ESRs persisted." (PMID 31296171, 2019). "The cause of uveitis was established in 19/20 (95%) of patients with ESR ≥ 60 mm/h and/or CRP ≥ 60 mg/L." (PMID 30411142, 2019). "Levels of ESR and CRP were determined within 2 weeks and 1 week after onset of uveitis, respectively." (PMID 30411142, 2019). "In this sense, recurrent AAU in men under 40 years (as previously reported), with very high CRP and normal WBC seems to characterize SpA-associated uveitis." (PMID 30206560, 2018). "Moreover, it is also ill-defined whether uveitis associated with BD is characterized by altered levels of acute phase reactants such as high-sensitivity (hs) C-reactive protein (CRP) that may eventually exacerbate the inflammatory burst further modifying serum inflammatory cytokine levels." (PMID 24994946, 2014). "These include uveitis, HLA-B27, alternate gluteal pain, peripheral arthritis, a high erythrocyte sedimentation rate, an elevated C- reactive protein (CRP), recurrent oligoarthritis, and a low-grade radiographic sacroiliitis." (PMID 22650358, 2012). "Although patients with elevated anti-CD74 Abs seem to have a higher disease severity, with systemic inflammation (CRP) and extra-musculoskeletal manifestations (uveitis), the quality of health as noted by the EuroQol 5-domain questionnaire was not reduced in patients with elevated anti-CD74 Abs." (PMID 40063233, 2025). "However, CRP levels were higher in the uveitis recurrence group, and the duration of adalimumab treatment was significantly longer." (PMID 41007651, 2025). "The HR for cataract risk was notably higher for those with CRP levels 1 mg/dL or more compared with those without uveitis." (PMID 38949811, 2024).